MMP9 (matrix metallopeptidase 9)
Diseases named in the same sentence as MMP9 in open-access papers (continued):
Sharing a sentence is not in itself a finding about the gene and the disease.
gastric cancer (continued). "Our findings are consistent with reports that MTAP expression in gastric carcinoma cells inhibits migration in a wound-healing assay, and that inhibition of MTAP causes increased expression of MMP-1 and MMP-9 in a human hepatocellular carcinoma cell line." (PMID 25387827, 2014). "The levels of HSP60 and matrix metallopeptidase 9 (MMP-9) antigen was evaluated by immunohistochemistry in 223 gastric carcinoma samples." (PMID 25207654, 2014). "ALDH1A1 and matrix metallopeptidase 9 (MMP-9) was evaluated by immunohistochemistry in 216 gastric carcinoma samples." (PMID 25253129, 2014). "Transfection of si-CCND1 and si-Ets1 resulted in decreased expression of cyclin D1, pRB, Ets1 and MMP-9 in gastric cancer cells, respectively, when compared to those transfected with scramble siRNA (si-Scb)." (PMID 23383271, 2013). "A Shh-dependent increment in the expression and in the activity of MMP9 has also been reported in gastric cancer cells, correlating with the invasive capacity of these cells." (PMID 23667589, 2013). "In conclusion, the NF-κB p65 inhibitor, SN50, inhibited the invasiveness of the gastric cancer cells by downregulating the protein expression of MMP-9, PCNA and VEGF and upregulating the protein expression of TIMP-1." (PMID 24137341, 2013). "They showed that 67LR promotes the invasive and in vivo metastatic ability of gastric cancer cells via increasing a serine protease family member, Urokinase-type plasminogen activator (uPA) and Matrix metalloproteinase 9 (MMP9) expression." (PMID 24216696, 2013). "Increased activation of Notch signaling observed in skeletal muscle of mdx;Mmp9+/− mice is in agreement with a previous report of a direct negative regulation between Notch2 and MMP-9 in human gastric carcinoma cells." (PMID 23977226, 2013). "Immunohistochemistry for NF-κB p65 (RelA), phospho-Tyr705-STAT3 (pSTAT3), or matrix metalloproteinase 9 (MMP9) was performed on tissue array slides containing 255 gastric carcinoma specimens." (PMID 23402362, 2013). "HSP90 and matrix metallopeptidase 9 (MMP-9) antigen expression was evaluated by immunohistochemistry in 322 advanced gastric carcinoma samples." (PMID 23638161, 2013). "One study has measured both serum and plasma MMP9 levels in patients with gastric cancer and controls." (PMID 22433968, 2012). "In gastric carcinoma, high levels of CLDN4 have been found to be significantly associated with MMP-9 expression, which in turn can degrade type IV collagen of ECM and facilitate cancer cell invasion." (PMID 23236365, 2012). "For one example, Runx3 has been shown to suppress gastric cancer metastasis through the inactivation of MMP-9 by the upregulation of TIMP-1." (PMID 21904555, 2011). "We found that coculture of gastric cancer cells with H. pylori induces expression of mRNAs encoding IL-8, VEGF-A, angiogenin, urokinase-type plasminogen activator, and MMP-9 by gastric cancer cells." (PMID 20369064, 2010). "In our study, it was showed that downregulation of CD147 expression in human gastric cancer cells reduced the secretion of MMP-2 and MMP-9, thus inhibited the invasion ability of gastric cancer cells through the reconstituted basement membrane in vitro." (PMID 20525232, 2010). "The gastric cancer-related overexpression of PTPRA and MMP9 has previously been implicated but the association between copy number and overexpression has not been reported." (PMID 20187983, 2010). "Our unpublished data also proved that isoproterenol stimulated the expression of MMP-2 and MMP-9 in gastric cancer cells mainly through activating STAT3." (PMID 20939893, 2010). "AhR pathway activation enhances gastric cancer cell invasiveness likely through a c-Jun-dependent induction of MMP-9." (PMID 19371443, 2009). "Taken together, we suggest that silibinin down-regulates TNF-α-induced MMP-9 expression through inhibition of the MEK/ERK pathway in gastric cancer cells." (PMID 19924065, 2009).
gastric cancer (continued). "In the present study we determined the effect of silibinin on MMP-9 expression in gastric cancer cells." (PMID 19924065, 2009). "In this study we determined the effect of silibinin on TNF-α-induced MMP-9 expression in gastric cancer cell lines." (PMID 19924065, 2009). "In conclusion, we determined the effect of silibinin on TNF-α-induced MMP-9 expression in gastric cancer cells." (PMID 19924065, 2009). "To corroborate these observations, we now assessed MMP-2 and MMP-9 with new techniques in an expanded group of gastric cancer patients (n=81) and included for comparison MMP-7, MMP-8 and the tissue inhibitors of MMPs, TIMP-1 and -2." (PMID 16538217, 2006). "In a pioneer study, we showed 10 years ago that enhanced tissue levels of the matrix metalloproteinases (MMPs) MMP-2 and MMP-9 in gastric cancers, as determined by zymography, were related with worse overall survival of the patients." (PMID 16538217, 2006). "We assessed the levels of MMP-2 (gelatinase A) and MMP-9 (gelatinase B) in 50 gastric carcinomas and corresponding mucosa using quantitative gelatin zymography." (PMID 8695357, 1996). "Finally, in an effort to translate these findings into a non-invasive setting, we screened the serum of gastric cancer patients and healthy individuals for MMP9 expression." (PMID 41041068, 2025). "In gastric cancer, the roles of MMP2 and MMP9 have been described extensively in the literature compared to other MMPs, with both enzymes proposed as novel biomarkers for gastric cancer prognosis, indicating a major role in the gastric cancer metastatic process." (PMID 40906383, 2025). "In other tumors, exosomes rich in matrix-degrading enzymes can facilitate cancer cell dissemination to both primary and metastatic sites, suggesting that the MMP9 serum of gastric cancer patients could be related to the metastatic progression of the disease." (PMID 40906383, 2025). "Similarly, Nar (20, 40, and 80 μM) downregulated MMP-2 and MMP-9 expression in SGC-7901 gastric cancer cells, further supporting its metastasis-inhibitory potential." (PMID 40563423, 2025). "However, previous studies have reported that elevated PRSS2 expression correlates with poor prognosis in gastric, breast, and prostate cancers, and promotes epithelial–mesenchymal transition in gastric cancer by upregulating MMP-9." (PMID 41141930, 2025). "In summary, we emphasize the cancer-specific nature of MMP9 and underscore the potential of N-glycosylation, particularly the potential acquisition of trimmed glycosignatures, to enhance patient stratification strategies in gastric cancer." (PMID 41041068, 2025). "Indeed, MMP-9 inhibition increased the efficacy of chemotherapy and decreased metastasis to the lungs in a mouse model of gastric cancer." (PMID 39555068, 2024). "The key targets of Zuojin pill MMP1, MMP3, and MMP9 play a therapeutic role in gastric cancer." (PMID 39086391, 2024). "We note that key nodes such as COL1A1, COL1A2, JUN, MMP9, APOE, and FOS displayed strongest strength of interactions in the network, suggesting that these genes are key genes associated with other proteins in gastric cancer." (PMID 39044041, 2024). "High levels of MMP-2, MMP-9, and vascular endothelial growth factor (VEGF) have been closely linked to cell growth, dissemination, metastasis, and the development of new blood vessels in gastric cancer." (PMID 38374934, 2024). "Total saponins of panax can reduce the expression of Vemintin, SNAIL, MMP2 and MMP9 and increase the expression of P21, Caspase-3 and Bax in gastric cancer cell lines, thus promoting apoptosis of tumor cells and hindering their proliferation, migration and invasion." (PMID 38817861, 2024). "In the present study, a subcluster of neutrophils with high-activity phenotypes accounted for a major proportion of PB samples after treatment, which also highly expressed well-known tumor-promoting genes of gastric cancer including MMP9, S100A8, S100A9, PORK2, and TGF-β1." (PMID 37333017, 2023).
gastric cancer (continued). "Thus, many additional signaling modulators should be explored to define sulforaphane suppression of nicotine-induced MMP-9 expression in AGS gastric cancer cells." (PMID 35563563, 2022). "In short, DHCE destroyed F-actin microfilament to block cytoskeleton activation, and inhibited the protein expression of the Ras/Raf/ERK/MMP9 pathway to block the signal transmission of this pathway, thereby inhibiting the migration and invasion of gastric cancer cells." (PMID 35566048, 2022). "In a recent study, TAM-derived MMP9 was shown to support metastasis, and treatment with MMP9 inhibitors could reduce distant metastasis in gastric cancer." (PMID 35269560, 2022). "Matrix metalloproteinase-9 (MMP-9) plays a crucial role in gastric cancer metastasis." (PMID 35563563, 2022). "The effects of MMP-9 inhibitors on the treatment of gastric cancer have been widely reported." (PMID 35563563, 2022). "Furthermore, EP-CAM can regulate MMP2 and MMP9 in gastric cancer by activating the NFκB signaling pathway." (PMID 36107005, 2022). "Further understanding of MMP9 biology and ways to modulate MMP9 activity might enable the development of effective therapy in gastric cancer in the future." (PMID 35773363, 2022). "TNF, IL1B, and MMP9 play important roles in the occurrence and development of gastric cancer." (PMID 36200190, 2022). "However, the potential mechanisms by which sulforaphane inhibits MMP-9 expression are not fully understood in gastric cancer." (PMID 35563563, 2022). "A further study found that the blockade of the PI3K-AKT signaling pathway by using MMP9 proenzyme inhibitor could suppress the distant metastasis of gastric cancer cells." (PMID 34899944, 2021). "Interestingly, both IL-8 and IL-17 stimulate an expression of the NF-κB target gene MMP-9 in human gastric cancer cell lines MKN-1 and AGS, respectively, which enhances cell migration and invasion." (PMID 34440074, 2021). "Moreover, MMP-9-positive gastric cancer patients have worse outcomes than those with MMP-9-negative tumors; of note, MMP-9 silencing results in the inhibition of cell growth and invasion of SGC7901 gastric cancer cells in vitro and in vivo." (PMID 33562660, 2021). "Also, the RUNX3 signaling pathway regulating TIMP3 can be effective in MMP-9 activity in gastric cancer invasion." (PMID 34054953, 2021). "MMP-9 contributes to tumor metastasis via the sonic hedgehog signaling pathway in gastric cancer." (PMID 34707964, 2021). "In addition, the natural compound triallyl trisulfide (DATS) extracted from garlic can inhibit gastric cancer cell metastasis by up-regulating E-cadherin and down-regulating MMP-9." (PMID 34422902, 2021). "In addition, HDAC5 enhanced the invasiveness of gastric cancer cell lines by stimulating protein kinase C (PKC)/matrix metalloproteinase 9 (MMP9)." (PMID 34178647, 2021). "Then we explored whether the mRNA and protein levels of MMP9 were also well correlated with MICAL2 or MRTF-A in gastric cancer cells." (PMID 33842533, 2021). "In fact, MMP-9 associated cleavage and consequent shedding of tumor cell membrane proteins such as MIC-A, MIC-B and ULBP-2, lead to reduced NK associated tumor cell death in gastric cancer, lung adenocarcinoma and osteosarcoma." (PMID 34066355, 2021). "For instance, CORO3 depletion could suppress gastric cancer metastasis by reducing the expression levels of matrix metallopeptidase 9 (MMP9) and cathepsin K." (PMID 34026752, 2021). "MMP-9 expression in gastric carcinoma is correlated with various histopathological parameters." (PMID 34707964, 2021). "However, in vitro cell invasion of gastric carcinoma-derived cancer cells was only promoted when the TAM-like monocytes expressed MMP9." (PMID 33466303, 2021). "Some lines of evidence have shown that MMP-9 expression might be involved in gastric cancer invasion and is a predictor of outcomes in metastatic gastric cancer patients." (PMID 33233689, 2020).
gastric cancer (continued). "MMP9 upregulation and its negative association with prognosis in cancers such as gastric cancer has been reported and a monoclonal antibody aimed at MMP9 inhibition is currently in human trials." (PMID 33007872, 2020). "Similarly, a previous study indicated that tumor necrosis factor-α-induced matrix metallopeptidase-9 secretion from mesothelial cells promoted the metastatic dissemination of gastric cancer cells." (PMID 32139657, 2020). "Our data showed that BAG2 knockdown might suppress intercellular EMT process by down-regulating the expression of N-cadherin, MMP9, Vimentin and Snail, thereby reducing invasion and migration of gastric cancer cells." (PMID 32082999, 2020). "Moreover, MMP-9 levels were found to be significantly higher in the serum of gastric cancer patients when compared with those of controls." (PMID 32046329, 2020). "Moreover, MMP9 has been regarded as an essential marker for metastasis of cancers, including gastric cancer." (PMID 32293550, 2020). "The higher expression levels of both CXCL8 and MMP9 in a gastric cancer sample were also confirmed in the TCGA data when compared with a normal sample analyzed with GEPIA, and it was further found that the correlation between CXCL8 and MMP9 expressions was R = 0.49 (p = 0)." (PMID 31681401, 2019). "As the IL-6-induced transcriptional stimulation of MMP-9/2 results from the activation of STAT3 via the JAK2/STAT3 pathway in gastric cancer and AGS cells, we tested the STAT3 phosphorylation level in MKN-28 and AGS cells exposed to rIL-6 for different time points." (PMID 31817563, 2019). "Using a robust proteomic approach, we identified numerous molecules secreted into the omental tissue conditioned medium (CM) which may promote gastric cancer cellular aggressiveness (i.e., IL-6, IL-8, MMP9, FN1, and CXCL-5)." (PMID 31803630, 2019). "All these indicated that the CXCL8 and MMP9 coactivated bioprocess might be the consistent phenotype involved in PNI-related gastric cancer." (PMID 31681401, 2019). "To further study the mechanism by which IFT80 promotes gastric cancer cell invasion, we next examined whether the overexpression of IFT80-enhanced invasion ability of SGC-7901 cells is associated with p75NGFR and MMP9." (PMID 30453504, 2018). "The relationship between the level of MMP-9 in the gastric carcinoma environment and the malignant invasive phenotypes of gastric carcinoma, including lymph node metastasis, has been extensively studied, and the data suggest that MMP-9 plays important roles in the progression of gastric cancer." (PMID 30544870, 2018). "In addition, we suggested the importance of the MMP-9 secreted by host mesothelial cells in gastric carcinoma invasion by utilizing a reconstituted mesothelium consisting of a monolayer of peritoneal mesothelial cells layered on a Matrigel basement membrane." (PMID 30544870, 2018). "Among the MMPs, MMP-9 is closely correlated with tumor metastasis in various cancers, including gastric cancer, prostate cancer, and cervical cancer.Therefore, MMP-9 and other MMPs may be considered as effective targets for anti-cancer drugs." (PMID 28288190, 2017). "Simvastatin, a cholesterol-lowering drug, can sensitize the gastric cancer to the antitumor effects of capecitabine through suppressing the constitutive activation of NF-κB and expression of COX-2, cyclin D1, Bcl-2, survivin, CXC motif receptor 4, and MMP-9 proteins in gastric cancer cells." (PMID 28350359, 2017). "Moreover, a more direct link with MMP-9 was found whereby SLPI was shown to promote the metastasis of gastric cancer cells by increasing MMP-9 expression." (PMID 28561062, 2017). "Also, overexpression of the SLPI in gastric cancer cells increased the expression of FoxM1 target genes iMMP-2 and MMP-9 and promoted the migration of cancer cells by degrading collagen but FoxM1 was not examined." (PMID 29312532, 2017).
gastric cancer (continued). "In addition, NF-κB and STAT3 can synergistically influence the metastatic potential of gastric cancer cells through regulation of MMP-9 expression." (PMID 28350359, 2017). "Using the AEG‐1 stable knockdown cell lines in this model, we revealed that silencing of AEG‐1 expression not only inhibited tumour growth in parallel with decreased expression of eIF4E, MMP‐9 and Twist, but it also inhibited the lymph node and peritoneal metastasis of gastric cancer." (PMID 28661037, 2017). "IL-1β-induced NF-κB-dependent target genes include, for example, retinoid x receptor α; miR-425, which negatively regulates phosphatase and tensin homolog (PTEN) expression by targeting its 3′ UTR; MMP-9 in gastric cancer tissues and cell lines, that promotes cell proliferation and invasion." (PMID 28350359, 2017). "In addition, FOXO6 expression was positively correlated with MMP-9 among 192 gastric cancer tissues." (PMID 28404958, 2017). "Therefore, we also evaluated the correlation of Spondin-2 and MMP-9 expression in gastric cancer patients and found that Spondin-2 was positively correlated with MMP-9 expression in 174 gastric carcinoma tissues (r = 0.575, P < 0.001)." (PMID 28060752, 2017). "Grhl2 reduces the expression of MMP-2, MMP-7 and MMP-9, which may partly explain the inhibitory effect of Grhl2 on invasion and migration of gastric cancer." (PMID 28067907, 2017). "Moreover, overexpression of coronin-1C was found to correlate with lymph node spread and increased clinical stage in gastric carcinoma, possibly via the regulation of MMP-9 and cathepsin K." (PMID 28302118, 2017). "In the present study, we observed that 17β‐estradiol treatment significantly inhibited HBMMSCS‐mediated cell motility activity through suppressing IL‐8‐Src downstream target protein activation and expression, including Cas, paxillin, ERK1/2, JNK1/2, MMP9, tPA and uPA in human gastric cancer cells." (PMID 26945908, 2016). "However, opposite results also have been reported, one study showed that blockade of SAPK/JNK signaling was involved in the inhibition of matrix metalloproteinase 9 (MMP9) expression in human gastric cancer cells by a natural compound." (PMID 27421653, 2016). "In our study, we found that transfection of HIF-1α-induced-miR-421 significantly down regulated the epithelial biomarker E-cadherin and up regulated N-cadherin, Fibronectin, Vimentin, Snail, Slug, Twist, MMP-2, and MMP-9 in cisplatin treated gastric cancer cell lines." (PMID 27016414, 2016). "LINC00152 could directly bind to EGFR and activate EGFR signaling pathway and FENDER could suppress cell invasion and migration by downregulating FN1 and MMP2/MMP9 expression in gastric cancer." (PMID 27966444, 2016). "Luteolin also down-regulated MMP9 expression in both these gastric cancer cell lines." (PMID 25638174, 2015). "Gastric cancer metastasis-associated genes, including hypoxia-inducible factor (HIF)-1α, matrix metalloproteinase (MMP)-2, MMP-9, basic fibroblast growth factor (bFGF), and urease plasminogen activator (uPA) were measured by RT-sqPCR prior to and following transfection with the KAI1 gene." (PMID 26622792, 2015). "In an additional proof-of-principle approach, we measured the expression of MMP2, MMP7 and MMP9 in MKN45 gastric cancer cells before and after treatment with the mTOR inhibitor rapamycin to investigate the putative link between mTOR signalling and MMP expression in gastric cancer." (PMID 26652716, 2015). "Data from the present report indicates that MMP-9 may be key in gastric carcinoma malignancy, and implies that MMP-9 may serve as a novel biomarker in the diagnosis and prognosis of gastric carcinoma." (PMID 25621068, 2015). "The incidence of MMP-9 positive expression was observed to be greater in tumors with seromembranous invasion compared with non-invasive tumors, indicating that MMP-9 may contribute to invasion and tissue infiltration in gastric carcinoma." (PMID 25621068, 2015).